RNU6-1165P (RNA, U6 small nuclear 1165, pseudogene)
Gene: Small nuclear RNA gene on chromosome 10 (101,622,859 to 101,622,965, forward strand). Ensembl gene ENSG00000222051.
Homologues: Orthologues: chimpanzee U6 (100% identical), macaque U6 (96% identical). Paralogues in human: RNU6-797P (83% identical), RNU6-1094P (82% identical), RNU6-222P (82% identical), RNU6-454P (82% identical), RNU6-727P (82% identical), RNU6-1209P (80% identical), RNU6-1329P (80% identical), RNU6-28P (80% identical), RNU6-560P (80% identical), RNU6-992P (80% identical), RNU6-1047P (79% identical), RNU6-1056P (79% identical), and 1286 more.